SDHA (succinate dehydrogenase complex flavoprotein subunit A)
Diseases named in the same sentence as SDHA in open-access papers (continued):
Sharing a sentence is not in itself a finding about the gene and the disease.
tumor (continued). "This study explored the implications of overexpression and knockout of SDHA in various BC cell lines, aiming to understand their impact on the tumor phenotype." (PMID 40119440, 2025). "Knockdown of CS1 (citrate synthase 1), IDH (isocitrate dehydrogenase), or SDHa (succinate dehydrogenase-a) induced a significant drop in tumor growth." (PMID 40822358, 2025). "The B6 WT and the SDHA-KO animals were injected with the tumor cells and with either the anti-PD-1 antibody or rat IgG2a isotype control antibody." (PMID 41392980, 2025). "Previous reports indicate that increased succinate dehydrogenase complex flavoprotein subunit A (SDHA) activity enhances mitochondrial metabolism in tumor cells, leading to changes in basal and maximal OCR." (PMID 38396817, 2024). "Thus, the proband tumor may result from a somatic SDHA truncating variant and other mutations." (PMID 39464303, 2024). "The SDH up-regulation in combination with the depletion of OGDH can well explain the depletion of succinate observed in tumours compared to healthy tissue, as illustrated by the joint up-regulation of both the abundance and ocEAn score of SDHA in TT vs. NAT." (PMID 38969985, 2024). "The SDHA gene encodes one of four subunits in the succinate dehydrogenase (SDH) complex, which functions as tumor suppressors." (PMID 38770192, 2024). "The comparison of adjacent normal tissues to the tumor tissue in the same tissue sections of multiple patient samples revealed compelling evidence of decreased functional or flavinated SDHA in tumor tissue using SDHB levels as an indicator." (PMID 37945749, 2023). "Immunohistochemistry showed a loss of SDHB expression in the tumour tissue, which indicates SDH deficiency that can be associated with loss of SDHA as well." (PMID 37507557, 2023). "It was recognised that there is currently limited knowledge regarding the full phenotype and penetrance of tumours in individuals with SDHA PGVs." (PMID 35260474, 2023). "The SDHA overexpressing tumor cells are highly metabolically active, relying on both glycolysis and oxidative phosphorylation in mitochondria to meet their energy requirements." (PMID 36291881, 2022). "By applying GSMMs, this study identified fumarate hydratase (FH) as a conserved gene for tumor growth in all liver cancer patients, whereas succinate dehydrogenase complex subunit A (SDHA) was predicted to be important for tumor growth in 60% of patients." (PMID 35121805, 2022). "Oncogenic transcription factors such as Myc induced acetylation-dependent deactivation of SDHA, which resulted in cellular succinate accumulation and consequently trimethylated histone H3 Lys 4 (H3K4me3) activation and expression of tumor-specific genes." (PMID 36551845, 2022). "Lastly, we performed a drug screening to identify agents specifically targeting the SDHA overexpressing tumor cells." (PMID 36291881, 2022). "We showed that shikonin exhibited a profound anti-tumor efficacy and selectivity towards SDHA overexpressing tumor cells in vitro superior to that observed with traditional chemotherapy." (PMID 36291881, 2022). "The SDHA overexpression strongly sensitized cancer cells to shikonin, which exhibited a profound anti-tumor efficacy superior that seen with traditional chemotherapy." (PMID 36291881, 2022). "Here, we uncover a critical role of the PIKE-A/STAT3/FTO/SDHA axis in promoting mitochondrial metabolism, which was a benefit for tumor growth." (PMID 36232604, 2022). "We found higher SUCNR1 and SDHA expression in tumor tissue from patients with poor locoregional control." (PMID 33916314, 2021).
tumor (continued). "Germline variants in SDHA, like other SDHX genes, can predispose to the development of PPGL but penetrance for these tumours is estimated to be under 10% from studies of relatives of probands diagnosed with PPGL and analysis of population databases." (PMID 33854214, 2021). "Lastly, all the described patients carried two mutational events at the SDHA locus, either the loss of the wild-type allele or a second somatic event in compound heterozygosity, in full agreement with the two-hit hypothesis of tumor suppressor genes inactivation." (PMID 35059314, 2021). "Instead, we found that succinate dehydrogenase (SDHA) was higher expressed in the tumor mass of caspase-4 positive NSCLC patients compared to the non-cancerous tissues." (PMID 33014287, 2020). "For the tumor suppressors, there are 3 up-regulated genes (mutations: POLE; CNAs: DNMT3B, RECQL4) and 2 down-regulated genes (CNAs: SDHA; fusions: ZFHX3)." (PMID 32934781, 2020). "Conversely, one tumor pair shared missense mutations in three genes (EMSY, SMAD4, and POM121L12) and gene copy number amplification of three genes (SDHA, TERT, and EGFR)." (PMID 33139840, 2020). "This shifted equilibrium was balanced by the anaerobic LDH activity and valine/proline/SDHA-induced TCA cycle in order to provide the dysregulated glucose metabolism to provide ATP to the tumor cell in order to survive and proliferate." (PMID 33014287, 2020). "In this study, we found that the TCA cycle was supported by higher expression of SDHA in caspase-4 positive tumor tissues." (PMID 33014287, 2020). "The SDH complex consists of four subunits (SDHA, SDHB, SDHC, and SDHD), and a deficiency of this enzyme is known to activate tumor formation through dysregulation of HIF activity." (PMID 31817761, 2019). "Biallelic inactivation of one of the four SDH subunit genes (SDHA, SDHB, SDHC, SDHD) is the most common mechanism causing SDH deficient (dSDH) tumours." (PMID 31308404, 2019). "The SDH (succinate dehydrogenase) respiratory complex with a role in the Krebs cycle and oxidative phosphorylation has four subunits encoded by 4 SDHx genes-SDHA, SDHB, SDHC, and SDHD that act as tumor suppressors." (PMID 30854332, 2019). "SDHA (subunit of complex II) levels were significantly lower in the tumor periphery than in the tumor center (p < 0.05) and in adjacent normal tissue (p < 0.001)." (PMID 31167495, 2019). "Given recently shown high incidence and low penetrance of SDHA variants, we performed NGS analysis of non‐tumor tissue of the patient to exclude the possibility of these mutations being already present in the germline of the patient." (PMID 31124195, 2019). "Nevertheless, it was catalogued as pathogenic in the CGC database (pathogenicity score of 0.81), and has been suggested that SDHA can act as a tumor suppressor gene." (PMID 31316139, 2019). "The primary tumor of SDHA-related metastatic PHEO/PGL was found to be highly recurrent within a short period of time (median 12 months) after complete resection." (PMID 30854332, 2019). "Based on the allele frequency of SDHA and KIT mutations, our tumor is best defined as SDH‐deficient GIST in which SDH loss is most likely the oncogenic driver." (PMID 31124195, 2019). "Additional testing included normal tumour tissue SDHA/SDHB immunohistochemistry and a normal g-banded karyotype to exclude a translocation involving chromosome 3." (PMID 31795919, 2019). "SDH is comprised of four nuclear encoded subunits (SDHA, B, C and D), and germline mutation in any of these SDH subunits is associated with a variable risk of developing neoplasia." (PMID 28738844, 2017). "Relative GUSB and SDHA expression was up-regulated in SW620 (line derived from secondary tumor), significantly in case of GUSB." (PMID 27339468, 2016).
tumor (continued). "Five genes encoding subunits of the succinate dehydrogenase (SDH) complex (SdhA, SdhB, SdhC, and SdhD) and the enzyme that flavinates SdhA are the leading tumor suppressor genes in familial PGL." (PMID 23451094, 2013). "Tumor phenotypes according to the SDH status were SDHA(+)/SDHB(+) > SDHA(–)/SDHB(–) > SDHA(–)/SDHB(+) > SDHA(+)/SDHB(–) in order of frequency." (PMID 23888270, 2013). "In this study we assessed the RNA quality of 738 tumour samples before pre-amplification and evaluated the pre-amplification success by measuring the expression of two low abundant reference genes (SDHA and HPRT1)." (PMID 19930725, 2009). "Consequently, limited citrate export for lipid production, combined with increased glutamine influx via anaplerotic reactions, likely contributes to the accumulation of citrate, isocitrate, and aconitate in SDHA-overexpressing tumor cells." (PMID 40563592, 2025). "Whereas individuals with paternally‐inherited SDHD PVs have an SDH‐related tumor risk over 40%, the risk for SDH‐related tumors in someone with an SDHA PV may be as low as 1.7%." (PMID 39927693, 2025). "Actually, few SDHA mutations were classified as VUS, probably due to the still low frequency of these alterations and to the absence of hotspot mutation domains, which is the typical mutational profile expected for tumor suppressor genes." (PMID 41407759, 2025). "Treatment of SDHA-KO B6 animals with anti-PD-1 demonstrated similar tumor control to isotype control antibody-treated KO animals, demonstrating that deficiency of SDHA enhanced CD8+ T cell–mediated antitumor immunity to a similar degree as the treatment with anti-PD1 therapy." (PMID 41392980, 2025). "TYRO3, a TAM family receptor tyrosine kinase, and SDHA, a mitochondrial enzyme involved in succinate metabolism, may contribute to tumor progression and represent emerging therapeutic vulnerabilities." (PMID 41373665, 2025). "However, despite demonstrating similar CD4+ mediated GVHD, the allorecipients of SDHA-KO and WT cells still demonstrated similar tumor-related mortality, demonstrating similar magnitude of preservation of CD8+ T cell–mediated GVT effects after allo-HCT." (PMID 41392980, 2025). "Similarly, MYC-mediated SDHA acetylation plays a crucial role in tumor cell growth via epigenetic regulation." (PMID 40186663, 2025). "Together, these data indicate that the majority of m+4- and m+5-labeled TCA cycle intermediates with both tracers ([U13C]glucose and [U13C]glutamine) were produced by [U13C]glutamine, and that glutamine showed significantly increased flux into the TCA cycle in tumor cells with SDHA overexpression." (PMID 40563592, 2025). "Furthermore, by employing HRA-MS and stable-isotope tracing, we discovered that tumor cells with SDHA overexpression show elevated levels of αKGDH complex and increased glutamine-derived carbon flux into the TCA cycle when compared to controls." (PMID 40563592, 2025). "Consistently, our in vivo study showed that the SDHA-overexpressing mFTE tumors exhibited significantly increased tumor growth and reduced mouse survival due to metastatic burden when compared with isogenic tumors with SDHA knockdown or unrelated tumors with low SDHA expression." (PMID 40563592, 2025). "Notably, SDHA (succinate dehydrogenase complex subunit A), a tumor suppressor that allows cells to grow in low oxygen conditions, was markedly downregulated by SOCS1." (PMID 38254783, 2024). "Optimizing SDHA surveillance options for patients requires consideration of penetrance and evaluation of the threshold at which screening is optimally beneficial for early tumor detection." (PMID 38770192, 2024). "However, the acetylation of these proteins has been confirmed to play a role in the regulation of tumor development, including SDHA, IDH1, and HMGB1." (PMID 38831454, 2024). "There are minimal data on the occurrence of a second tumour in individuals with an SDHA PGV." (PMID 35260474, 2023).
tumor (continued). "An association exists between germline SDHA mutations and GIST onset, supporting the idea that GISTs develop alone as the only tumor disease due to SDHA, and not in association with other tumors." (PMID 36980917, 2023). "Hypermethylation was higher in SDHB-mutated PPGL when compared to SDHA, SDHC and SDHD cases, which may explain the greater metastatic potential of SDHB-mutated tumours." (PMID 35938916, 2022). "Moreover, the SDHA overexpression strongly sensitized cancer cells to shikonin, which exhibited a profound anti-tumor efficacy superior to that seen with traditional chemotherapy." (PMID 36291881, 2022). "123I-MIBG and 111In-pentetreotide scintigraphy should not be used as first-line imaging studies for initial tumour screening in asymptomatic SDHA, SDHB, SDHC or SDHD-pi mutation carriers (Grade A)." (PMID 34021277, 2021). "Loss of the SDHA wild-type allele was confirmed with a panel-based sequencing assay (see Materials (subjects) and methods section) where variant allele fraction (VAF) was 0.42 in the blood sample from the mother and 0.92 in her tumour sample." (PMID 33854214, 2021). "This study therefore shows that, differently from previously stated, the SDHA-mutant GIST patient is almost exclusively a germline SDHA-variant carrier that is prone to develop the tumor throughout his entire life and not just in his early adulthood." (PMID 35059314, 2021). "Conversely, negative immunohistochemistry for SDHB and SDHA is only seen in tumours with SDHA mutations." (PMID 34834591, 2021). "Furthermore, SDHA high expression inhibited proliferation and invasion in MM cell lines and enhanced the anti-tumor and synergistic effect of chemotherapeutics." (PMID 33014881, 2020). "In a word, deficiency of SDHA may lead to tumorigenesis in some cancers and SDHA can be regarded as tumor suppressor gene in these cancers." (PMID 33014881, 2020). "We hypothesized that the intratumor heterogeneity and haploinsufficiency could explain this contradictory result if the majority of the SDHA gene in the neoplasms was unmutated, thereby preserving the conformational structure of most of the SDHA protein." (PMID 33031286, 2020). "A novel variant in SDHA on chromosome 5p15 was identified in the tumor tissues of both patients but not in the peripheral blood, indicating that it was a somatic mutation." (PMID 33031286, 2020). "The tumor had a mixed histology pattern of high-grade papillary and collecting duct carcinoma and characteristic pale eosinophilic cytoplasmic inclusions like SDHB-deficient RCC; this is the first report that identifies SDHA inactivation in RCC93." (PMID 31372201, 2019). "We suggest especially radionuclide imaging three-four months after presumed complete resection of a metastatic/multiple PCC, any PGL, or high-risk (SDHA/B) mutation carrier in the case of post-operative abnormal biochemistry or non-functional tumor." (PMID 31597347, 2019). "We hypothesize that based on the allele frequency of SDHA and KIT mutations the tumor is best regarded as SDH‐deficient GIST in which the SDHA mutation represents the most likely driver mutation." (PMID 31124195, 2019). "Importantly, the expression of SDHB is lost in all SDH-deficient neoplasms irrespective of the specific SDH subunit (SDHA, SDHB, SDHC, and SDHD) affected by a genetic mutation." (PMID 37999735, 2024). "The c-Myc oncogene-mediated inhibition of succinate dehydrogenase complex subunit A (SDHA) via acetylation and activation of deacetylase degradation pathways leads to cellular succinate accumulation, further triggering H3K4me3 activation, tumor-specific gene expression, and, thus, tumor progression." (PMID 37046597, 2023). "The working group felt that due to the low penetrance of SDHA PGVs outside the context of a personal or family history of SDHA-associated tumours, in this situation we would not recommend any surveillance in affected individuals or predictive testing for other family members." (PMID 35260474, 2023).
tumor (continued). "Prospective research studies and/or service evaluations are undertaken to define of the natural history of individuals with SDHA PGVs identified with SDHA-associated and SDHA non-associated tumours and consider if specific genetic or environmental factors alter the penetrance in SDHA carriers." (PMID 35260474, 2023). "Therefore, SDHB-absent tumor immunostaining suggests the presence of an inactivating germline SDHA, SDHB, SDHC, or SDHD followed by a somatic loss in the second allele of the gene." (PMID 36091175, 2022). "Based on this collective knowledge, we propose that SDHA overexpression could promote cell survival and ability to proliferate in anchorage-independent conditions, which is in contrast to SDHA-low tumor cells that more efficiently proliferate, migrate and invade in adherent cell cultures." (PMID 36291881, 2022). "Besides, the tumor has an SDHA or SDHC alteration is also possible." (PMID 33612108, 2021). "Chidamide could exert the function of anti-tumor by increasing expression of SDHA in MM." (PMID 33014881, 2020). "In addition, genetic screening for SDHA mutations was only performed in SDHA immunohistochemically-negative tumor PCC1." (PMID 31052272, 2019). "Mutations in tumor-suppressing genes encoding subunits of the succinate dehydrogenase (SDH) complex (SDHA, SDHB, SDHC, and SDHD, i.e. SDHx genes) and the required assembly factor that flavinates SDHA (SDHAF2) can inhibit SDH activity and thereby cause hereditary and (apparently) sporadic PPGL." (PMID 29464059, 2018). "In the other two cases for which germline DNA was not available, sequencing of the tumor revealed homozygous missense SDHA mutations, presumably due to a germline point mutation accompanied by allelic losses surrounding the chromosome 5p15 locus, identified using high-density SNP copy-number arrays." (PMID 23730622, 2013). "Since only the hot spot exons 9 and 13 of SDHA gene were investigated in this case, we cannot exclude the possibility of a germline mutation in a different exon, in keeping with a ‘two-hit’ mechanism of loss of function, implicated in most other SDH-deficient neoplasias." (PMID 22974104, 2012). "Since shikonin effectively eliminates SDHA-overexpressing tumor cells while targeting LRPPRC, this suggests a potential unexplored interaction or dependence between SDHA and LRPPRC proteins." (PMID 40563592, 2025). "Immunohistochemical staining revealed diffuse KRT7, vimentin, PAX8, e-cadherin, SDHA, SDHB and fumarate hydratase expression in tumor cells." (PMID 39980061, 2025). "This suggests that SDHA-overexpressing cancer cells are particularly vulnerable to the LRPPRC inhibition, which leads to tumor cell death." (PMID 40563592, 2025). "SDHA encodes a mitochondrial enzyme; its amplification may alter cellular metabolism through changes in succinate and α-ketoglutarate levels, potentially influencing the activity of epigenetic regulators such as TET2 and ASXL1, and immune modulation within the tumor microenvironment." (PMID 41373665, 2025). "The FC in gene expression of each marker in tumour samples relative to healthy controls was determined using the 2− ΔΔCt method normalised to the average of 7 housekeeping genes (YWHAZ, CYC1, SDHA, TBP, GAPDH, UBC and 18s RNA)." (PMID 41034696, 2025). "We primed WT and SDHA-KO CD8+ T cells with irradiated BALB/c splenocytes and cocultured primed CD8+ T cells with BALB/c-derived A20 tumor cells." (PMID 41392980, 2025). "However, there were no somatic mutations in SDHA found in the tumor tissues." (PMID 39464303, 2024). "Another study reported the reduced expression of NDUFS4, SDHA, UQCR2, MT-CO1, and ATP5F1A in tumor samples from 94 PCa patients who had undergone radical prostatectomy after tumor diagnosis." (PMID 36901912, 2023). "SDH deficiency is mainly caused by the biallelic inactivation of one of the four SDH subunit genes (SDHA, SDHB, SDHC, and SDHD) according to the classic tumor suppressor gene model." (PMID 36980917, 2023).